ENO1 (enolase 1)
Diseases named in the same sentence as ENO1 in open-access papers (continued):
Sharing a sentence is not in itself a finding about the gene and the disease.
cancer (continued). "The glycolytic enzyme enolase 1 (ENO1) has been shown to regulate the development of various cancers." (PMID 31431517, 2019). "A functional consequence of these alterations has been observed both, in vitro and in vivo as ENO-1 depleted cancer cells exhibited decreased growth, survival and clonogenic ability." (PMID 31106201, 2019). "Strikingly, knocking down ENO1 expression impaired cancer cell growth in vitro and in vivo, and it suppressed the Warburg effect in vitro." (PMID 31511554, 2019). "Cell surface bound ENO-1 has been detected on several cell types including immune, cancer and neuronal cells as well as bacteria." (PMID 31106201, 2019). "According to the well-known Warburg effect, cancer cells highly express almost all glycolytic enzymes, including ENO1, which is upregulated both at the mRNA and the protein level in several tumors including breast." (PMID 31416219, 2019). "On the cell surface of cancer cells, ENO-1 was reported to regulate migration, invasion and colony formation." (PMID 31106201, 2019). "ENO1, a key glycolytic enzyme, contributes to the known “Warburg effect” that is the high glycolytic rate of cancer cells, even in presence of oxygen, and necessary to support the biosynthetic requirements of uncontrolled proliferation." (PMID 31416219, 2019). "By conversing 2-phosphoglycerate into phosphoenolpyruvate, ENO1 performs crucial roles in aerobic glycolysis, and acts as a key contributor to Warburg effect in cancer cells." (PMID 31767835, 2019). "In lung cancer, knock down of ENO-1 decreased the pericellular fibrinolytic activity of cancer cells and thereby their invasion." (PMID 31106201, 2019). "After reaching a peak at stage III, ENO1 plasma expression at stage IV cancer appeared to be lower than that at stage III cancer although the difference was not significant." (PMID 29483925, 2018). "GRN A is also capable of inhibiting migration and invasion of HepG2 cancer cells by interacting with ENO1." (PMID 30301274, 2018). "Silencing of ENO1 in cancer cells promotes the adaptation to catabolic pathways, restores acetyl-CoA bulk through enhanced β-oxidation, and fuels the tricarboxylic acid (TCA) cycle by the cataplerotic reactions of tyrosine and glutamine catabolism." (PMID 30242159, 2018). "Mechanistically, we have provided the axis of ENO1-AMPK-Akt that controls the cancer-like PASMC phenotypes characterized by increased cell proliferation, de-differentiation, apoptosis resistance, and metabolic shift to glycolysis." (PMID 30242159, 2018). "By participating in anaerobic glycolysis (Warburg effect) and providing ATP, ENO1 is thought to promote cancer development and progression." (PMID 30518748, 2018). "Recent researches have shown that ENO1 plays an important role in several biological and pathophysiological processes, such as tumorigenesis, cancer invasion, and metastasis." (PMID 29483925, 2018). "Under the normal condition, the transcript level is more than 100-fold lower than that of ENO1 in a variety of normal and cancer cells such as NHBE, BEAS-2B and A549." (PMID 30518090, 2018). "Our previous study confirmed that the inhibitory effect of GRN A on cancer cells is associated with the interaction between GRN A and ENO1, and GRN A is capable of inhibiting the function of ENO1." (PMID 30301274, 2018). "After decades of research, scientists have demonstrated that besides its glycolytic function in normal processes, ENO1 also participates in several critical biological processes in cancer, including proliferation, migration, and invasion." (PMID 30518748, 2018). "Our results showed that the inhibitory effect of cancer cells growth was diminished significantly in cells with an overexpression of ENO1 in both BEL7402 and HepG2 cells, compared with that in the parent cells." (PMID 30301274, 2018). "We evaluated the expression of ENO1 in several cancer cell lines and found that ENO1 and Homer3 were potent partners of WBP2 in U251 cells." (PMID 29497031, 2018).
cancer (continued). "Comparative proteomics, as well as genomics and functional studies of several cancers, including PCa, have shown the overexpression of ENO1, but opposite levels, as we have evidenced, have been reported also." (PMID 29286311, 2017). "The Warburg effect is a metabolic reprogramming, which consists in a positive regulation exerted by the hypoxia-inducible factor (HIF) on the expression of glycolytic enzymes, such as ENO1, occurring when cancer cells are exposed to hypoxic conditions." (PMID 27906678, 2017). "Knocking down the expression of ENO1 results in suppression of cell growth, clone formation, and inhibition of the migration and invasion of cancer cells." (PMID 28415822, 2017). "More studies are needed to document if GRN A treatment of cancer cells is able to affect the interaction of ENO1 with plasminogen, uPA and uPAR." (PMID 28415822, 2017). "ENO1 silencing decreased cancer cell growth, survival and clonogenic capability in vitro, as evaluated by cell growth curve, MTT assay, and colony formation assay, respectively, without any evidence of apoptosis (data not shown)." (PMID 26734996, 2016). "ENO1 was silenced in a panel of human cancer cell lines, and we assessed the impact of this silencing through proteomic, biochemical and functional approaches." (PMID 26734996, 2016). "Herein, we are the first to demonstrate that ENO1 is one of the distinct proteins that is up-regulated in the retinal pigment epithelial cells by hypoxia, in conformity with the findings in cancer angiogenesis." (PMID 26882120, 2016). "Because of the potential utility of a cell permeable Enolase inhibitor for molecular targeted therapy of ENO1-deleted tumors, we systematically evaluated ENOblock as an inhibitor of Enolase in vitro and for selective killing of ENO1-deleted cancer cells." (PMID 28030597, 2016). "ENO1 is demonstrated to be up-regulated in the hypoxic cancer and brain cells under the control of the Hypoxia-inducible factor 1-α (HIF-1α)." (PMID 26882120, 2016). "Of particular significance, we showed that a pan-enolase inhibitor, PhAH, was able to induce a remarkable decrease of cancer cell proliferation in vitro, supporting the translationability of ENO1 inhibition." (PMID 26734996, 2016). "Unexpectedly, we found that cancer cells respond to ENO1 silencing by activating catabolic adaptations leading to restoration of pyruvate, acetyl-CoA bulk and oxidative phosphorylation." (PMID 26734996, 2016). "Overall, ENO1 silencing switched the typical aerobic glycolysis of cancer cells towards oxidative phosphorylation." (PMID 26734996, 2016). "Since ENO1-silenced cancer cells are blocked in cell cycle progression and undergo senescence, ENO1 remains an attractive target for therapeutic intervention in cancer." (PMID 26734996, 2016). "Here, we silenced ENO1 in human cancer cell lines and evaluated its impact through proteomic, biochemical and functional approaches." (PMID 26734996, 2016). "In several human cancers such as breast cancer, lung adenocarcinoma, glioma, and hepatoma, ENO1 is known to be over-expressed and its expression correlates positively with tumor progression, angiogenesis and venous invasion." (PMID 26882120, 2016). "Several reports have demonstrated that ENO1 is overexpressed in many types of cancer, including breast, lung, and prostate cancers." (PMID 26551021, 2015). "ENO-1, ANX2, CK8 and ACT are the best-described PLG-Rs until now, which are linked to the pathogenesis of human cancer." (PMID 25407528, 2014). "The vast majority of the studies dedicated to the role of ENO-1 in cancer biology describe changes in total ENO-1 expression and the impact of these alterations on cell proliferation, viability, and activation of gene transcription." (PMID 25407528, 2014). "Since surface ENO1 is present in several cancers, these results provide the rationale to develop therapeutic approaches targeting ENO1 in the future." (PMID 23894455, 2013).
cancer (continued). "Alpha-enolase (ENO1), which was found to be over-expressed in our study, has also been reported to be upregulated in several types of cancer." (PMID 23914992, 2013). "Enolase-1 is expressed at the cell surface where it promotes cancer invasion, and is subjected to a specific array of post-translational modifications, namely acetylation, methylation and phosphorylation." (PMID 23845056, 2013). "Normally, the cell can survive in the presence of ENO1 deletion, however, if ENO2 is silenced, the cancer cell with the ENO1 deletion dies." (PMID 23006971, 2012). "Quantification of immunohistochemistry was carried out using Quick score and the results showed cytoplasmic ENO1 overexpression in 9 of the 50 carcinomas (18%)." (PMID 22014164, 2011). "ENO1 and PGK1, linked to aerobic glycolysis, are correlated with the cancer prognosis." (PMID 41328179, 2026). "However, in malignant tumors with reserved prognosis, ENO1 showed moderate staining in approximately 50% of samples (E, F) and strong in the other 50% (A, C), while ZEB1 showed consistently strong intensity." (PMID 40005870, 2025). "Furthermore, ENO1 can also act as a DNA or RNA binding protein to regulate transcription and translation in cancer cells." (PMID 40533767, 2025). "According to an earlier study, the ENO1 signaling pathway could be a viable target for cancer therapies." (PMID 40740998, 2025). "Furthermore, our findings highlight a critical moonlighting function of ENO1 in GC and underscore its potential as a novel target for cancer therapy." (PMID 40701248, 2025). "Moreover, in vivo experiments demonstrated that upregulation of SPP1 in ENO1-KO cancer cells enhanced CD206+ TAMs infiltration in TME." (PMID 40665335, 2025). "The abundance of cancer cells decreased, while T cell abundance increased in ENO1-KO tumors." (PMID 40665335, 2025). "We chose ENO1 for further characterization because of its critical role in glycolysis and cancer." (PMID 40298941, 2025). "Alpha-enolase (ENO1) has been shown to facilitate the Warburg effect in cancer cells." (PMID 40519928, 2025). "Recent studies have revealed that ENO1 not only drives metabolic reprogramming in cancer cells but also acts as a moonlighting protein, actively secreted into the TME via exosomes or in soluble form, thereby regulating intercellular communication and immune evasion." (PMID 41353343, 2025). "Recent studies corroborate the multifaceted role of ENO1 in cancer." (PMID 41179678, 2025). "The ELISA assay showed that BMDMs or THP-1 cells from WT cancer cells could secrete higher SPP1 than those from ENO1-KO cancer cells." (PMID 40665335, 2025). "Moreover, the RNA binding abilities of ENO1 and PKM have been linked to cancer progression and proliferation." (PMID 41175344, 2025). "Additionally, ENO1 exhibits moonlighting functions on the cell surface and acts as a plasminogen receptor, promoting cancer hyperplasia and metastasis by inducing angiogenesis." (PMID 40486495, 2025). "Given ENO1’s oncogenic roles and high expression in cancers, it is a promising therapeutic target." (PMID 40734168, 2025). "Overall, ENO1’s dual functions as an enzyme and plasminogen receptor underscore its significance in cancer progression and highlight its potential as a therapeutic target for cancer treatment." (PMID 38611852, 2024). "Furthermore, ENO1 participates in regulating integrin expression, which is a critical player in cancer cell adhesion, invasion, and metastasis." (PMID 38611852, 2024). "Thus, ENO1 was considered an important target in cancer treatment and acted as a good prognostic indicator to monitor the disease progression." (PMID 38515460, 2024). "MBP-1 inhibits cancer, whereas ENO1 has the opposite effect." (PMID 39576845, 2024). "Of note, recent studies have revealed that anti-ENO1 antibody was associated with the CD44+ subpopulation, blocked the malignant transformation of CSCs, and prevented cancer metastasis and prolonged survival." (PMID 38515460, 2024).
cancer (continued). "ENO1 and IL-32 commonly act on the development and progression of cancer." (PMID 38675491, 2024). "ENO1 is ubiquitously expressed in most human tissues and is overexpressed in multiple cancer types." (PMID 39717827, 2024). "Similarly, GEPIA data also showed that ENO1 expression was high in most cancer types, which was consistent with TIMER analysis." (PMID 36845730, 2023). "Alpha-enolase (Eno1), which catalyses the conversion between 2-phosphoglyceric acid and phosphoenolpyruvic acid, is involved in many biological functions, including cellular stress, cancer metastasis and autoantigen activities." (PMID 37125075, 2023). "Enolase1(ENO1) is a glycolytic enzyme that has a crucial function in aerobic glycolysis by converting 2-phosphoglycerate to phosphoenolpyruvate and is a significant contributor to the Warburg effect in various cancers." (PMID 37807062, 2023). "ENO1, NDRG1 and NPM1 are reportedly associated with cancer as further discussed." (PMID 38097352, 2023). "The cytosolic catalytic function of ENO1 participates in glycolysis (or Warburg effect in cancer) and the extracellular function of ENO1 involved in plasmin-mediated pericellular proteolysis might both contribute to the lung fibrotic process." (PMID 37964270, 2023). "Blockade of ENO1 with antibodies has been demonstrated in previous pre-clinical studies of pancreatic and lung cancer as an effective anti-invasiveness/metastasis strategy to treat cancers." (PMID 37964270, 2023). "Furthermore, ENO1 acts as a plasminogen receptor on the cell surface and promotes cancer invasion and metastasis by angiogenic stimulation." (PMID 37807062, 2023). "PGAM1 and ENO1 are important glycolytic enzymes that catalyze the conversion of 3-phosphoglycerate to phosphoenolpyruvate and coordinate glycolysis and biosynthesis that are important in cancer progression." (PMID 37500057, 2023). "To investigate whether ENO1 affects the cancer cell malignant behaviors, we also performed function rescue experiments using T98G cells." (PMID 36494582, 2023). "Small molecule inhibitors of ENO-1 have been shown to inhibit cancer cell growth." (PMID 36768924, 2023). "In particular, a previous work discovered that PRMT5 monomethylates ENO1 at R50 to regulate its LPS‐induced translocation from the cytoplasm to the cell surface of lung epithelial cancer cells, thereby affecting the invasive properties of cancer cells." (PMID 36999124, 2023). "ENO1, also referred to as 2-phospho-D-glycerate hydrolase, is a multifunctional oncoprotein that is present both at the cell surface and in the cytoplasm, contributing to it displaying seven out of ten “hallmarks of cancer”." (PMID 36588153, 2023). "Interestingly, elevated ENO1 levels are shown to activate growth and migration in cancer cells via activation of multiple signalling pathways." (PMID 36564470, 2023). "The cancer-promoting effect of NMRAL2P can be weakened by ENO1 knockdown." (PMID 37810778, 2023). "This is consistent with the report that ENO1 regulates stem cell-like properties in cancer cells." (PMID 36845730, 2023). "Additionally, targeting TYRO3 can down-regulate ENO1 to inhibit the EMT process by interfering with energy metabolism in cancer cells." (PMID 37116196, 2023). "Indeed, downregulation of several glycolysis genes deeply involved in cancer progression (ENO1, ME1, SLC2A4RG, PFKL and DLAT) was confirmed by RT-qPCR in siRNF40-treated HCC1806 cells." (PMID 37770435, 2023). "Functional studies demonstrated that ENO1 depletion inhibited cancer cell aggressiveness." (PMID 35836227, 2022). "Given the role of ENO1 in anaerobic glycolysis and the metabolic switch in cancer cells, we hypothesized that it likely mediates the effects of lactate on the growth of cell line-derived organoids." (PMID 35443744, 2022).
cancer (continued). "On the cell surfaces, since ENO1, along with urokinase-type plasminogen activator, integrins, and cytoskeletons, are responsible for cell adhesion, depletion of ENO1 limits the migration ability of cancer cells." (PMID 35434271, 2022). "ENO1 is upregulated in various cancers, and the mechanism depends on the cancer type." (PMID 35078505, 2022). "The present analysis, performed on patients’ surgical resection specimens, showed that overexpression of ENO1 in tumoral cells was significantly correlated with disease advancement, the presence of metastases in regional lymph nodes, and shorter cancer-specific overall survival." (PMID 35204345, 2022). "The promising results from combinational citrullinated ENO1 and Vim peptides also should be further explored with chemotherapeutic targets in pilot clinical trials for their immunogenicity and safety in cancer patients, to open new possibilities of design immunotherapeutic strategies." (PMID 36612133, 2022). "For example, ENO1 is elevated in various tissue and involved in the oncogenesis of human cancers." (PMID 35504868, 2022). "Few studies show links between H. pylori infection and ENO1 expression in cancer cells." (PMID 36295613, 2022). "Indeed, lactate supplementation also increased the expression of ENO1 in the organoids, which was suggestive of distinct glucose metabolism profiles of cancer and non-cancer cells." (PMID 35443744, 2022). "Overall, these results suggested that ENO1 played different biological roles depending on the types of cancer while the exact mechanisms of action remain unclear." (PMID 35610567, 2022). "Additionally, Function experiments demonstrated that ENO1 depletion inhibited cancer cell aggressiveness, further indicating that ENO1 functions as a bad prognostic factor in BLCA." (PMID 35836227, 2022). "However, a very interesting direction of research in the area of anti-cancer treatment in the context of enolase is the use of ENO2 inhibitors in tumors that have an ENO1 deletion." (PMID 35628385, 2022). "In H&E staining, the number of cancer cells in the sh-ENO1 group was reduced." (PMID 35513377, 2022). "Besides, ENO1 “moonlights” on the cell surface and acts as a plasminogen receptor, promoting cancer invasion and metastasis by inducing angiogenesis." (PMID 35434271, 2022). "In addition, significant difference was also detected in ENO1 expression levels between the cancer tissues of low differentiation and those of high/moderate differentiation, suggesting the correlation of ENO1 with cellular differentiation." (PMID 36295613, 2022). "ENO1 plays critical and multifunctional roles in various physiological and pathological processes, including tumorigenesis, cancer invasion, and metastasis." (PMID 33968941, 2021). "Knockdown of ENO1 decreased cancer cell proliferation and metastasis in vitro and in vivo." (PMID 34944416, 2021). "Elevated levels of ENO1 were found in many types of cancer, including PDA." (PMID 33804240, 2021). "Whilst cancer cells are known to constitutively upregulate the expression of glycolytic enzymes, including ENO1, as a part of the “Warburg effect”, it remains unclear why these enzymes are concentrated at invadopodia." (PMID 34136381, 2021). "It was speculated that ENO1 was expressed with similar gene expression patterns in different cancers, and it participated in the occurrence and development of tumors in LUSC tissues." (PMID 34504528, 2021). "ENO1 is a crucial glycolytic enzyme involved in cell growth and is also reported as an oncogene that promotes metastasis by facilitating cell proliferation in multiple cancers including colorectal, lung, and prostate cancer." (PMID 33441968, 2021). "ENO1 contribute to the subsequent cellular response of cancer and may be a critical effector in PI3K/AKT pathway." (PMID 34671213, 2021). "Mechanically, the ginsenoside derivatives could down-regulated the expression of ENO1 in the cancer cells." (PMID 34671213, 2021).